BCL2 (BCL2 apoptosis regulator)
Diseases named in the same sentence as BCL2 in open-access papers (continued):
Sharing a sentence is not in itself a finding about the gene and the disease.
lung adenocarcinoma (continued). "Besides its effect on cell proliferation, recent studies have shown that nuciferine decreased the ratio of two apoptosis-related genes, Bcl-2/Bax, thus leading to cell apoptosis in human lung adenocarcinoma A549 cells." (PMID 33841152, 2021). "Forced LINC00461 expression decreased expression of miR‐195 and Bax, increased expression of HOXA10, MMP‐2, MMP‐9 and Bcl‐2, promoted cell proliferation, migration and invasion as well as tumour formation, and enhanced radiosensitivity of lung adenocarcinoma cells." (PMID 31967713, 2020). "Hence, this investigation provided a novel and potent BCL-2 targeting agent which possesses promising anticancer activity against lung adenocarcinoma with admirable in vivo efficacy." (PMID 31450709, 2019). "Here, we characterized bcl-2 interactome by mass spectrometry in human lung adenocarcinoma cells." (PMID 26866271, 2016). "Our findings showed for the first time that RBM5 overexpression induced autophagy in human lung adenocarcinoma cells, which might be driven by upregulation of Beclin1, NF-κB/P65, and downregulation of Bcl-2." (PMID 26923134, 2016). "Taken together, our results showed that activation of IL-11/IL-11R/STAT3 anti-apoptotic signaling could augment lung adenocarcinoma cells resistance to cisplatin-induced apoptosis by upregulating Bcl-2 and Survivin." (PMID 27922075, 2016). "The upregulation of Bcl-2 and Survivin were induced by IL-11 in the lung adenocarcinoma cell." (PMID 27922075, 2016). "Furthermore, miR-145 inhibited cell proliferation and promoted cell apoptosis through negatively regulating mTOR signaling pathway and decreasing MMP-2 and MMP-9 expression, the Bax/Bcl-2 ratio and the activity of the caspase-3 cascade in human lung adenocarcinoma A549 cells." (PMID 31582906, 2019). "To better elucidate the mechanisms of chemoresistance induced by IL-11, we found that IL-11 could attenuate cisplatin-induced apoptosis rate of lung adenocarcinoma cells accompanied with the activation of anti-apoptotic STAT3 signaling including Bcl-2 and Survivin overexpression." (PMID 27922075, 2016). "In the present study, we used 7,8-dihydroxycoumarin to treat A549 lung adenocarcinoma cells and then performed qPCR and western blotting to detect the ability of 7,8-dihydroxycoumarin to change the levels of anti-apoptotic pAkt, pIκBα, pNF-κB p65 and Bcl-2, as well as pro-apoptotic caspase-3." (PMID 23837071, 2013). "For example, in lung adenocarcinoma, FAM111B modulates the expression of BCL2 and BAG3 to facilitate cell proliferation, and FAM111B exhibits peak expression levels during the early G0 phase and late S phase of the cell cycle." (PMID 40781291, 2025). "Meanwhile, IHC analysis was conducted to assess the protein expressions of p-JAK2, p-STAT3, Bcl-2, Snail, and PTPRO in tissue sections obtained from ten cases of clinical lung adenocarcinoma specimens." (PMID 38182570, 2024). "In summary, our results indicate that the RUNX2 transcription factor participates in the intrinsic pathway of apoptosis avoidance through the transcriptional regulation of antiapoptotic genes BCL2, BCL-XL, and MCL1 in lung adenocarcinoma." (PMID 36510562, 2022). "In human lung adenocarcinoma A549 cells, upregulation of GLIPR1 stimulated cell proliferation by inducing the increased expression of Bcl-2, thus increasing resistance to the chemotherapeutic drug cisplatin." (PMID 34142021, 2021).
lung adenocarcinoma (continued). "Campesterol induced cell apoptosis through the mitochondrial pathway; it decreases the expression of BCL-2 and BCL-xL and increased the expression of BAX, BAD, BAK, and activating caspase 3 and caspase 9 in human lung adenocarcinoma (A549) cells." (PMID 33802602, 2021). "And Bcl-2 was down-regulated and cleaved PARP was up-regulated after knocking down PSME3, suggesting that PSME3 may affect the apoptotic process of lung adenocarcinoma through the PI3K/AKT pathway." (PMID 39346927, 2024). "An experimental study showed that the H. diffusa injection significantly reduced the survival of lung adenocarcinoma cells in vitro, inhibited the growth of BALB/c nude mice in vivo, and induced iron death of VDAC 2/3 regulation by Bax by inhibiting Bcl-2 gene." (PMID 38903989, 2024). "In order to further investigate the mechanism of inhibition of lung adenocarcinoma by WFEA, qRT-PCR and Western blot was carried out to detect the expression levels of PI3K-AKT signaling pathway related molecules (AKT, PI3K, MMP3, Caspase3 and Bcl-2)." (PMID 36949111, 2023). "Moreover, knockdown of EphA7 in lung adenocarcinoma has been found to increase apoptosis through regulation of BAX, Bcl-2, and caspase-3." (PMID 35103233, 2022). "In addition, in this context, it has been reported that in lung adenocarcinoma cells, OLE increased the Bax/Bcl-2 ratio and activation of caspase-9 and -3, leading to cell apoptosis." (PMID 35684123, 2022). "B-cell lymphoma 2 (Bcl-2), which is a downstream target of VGFR2 pathway, may also participate in lung adenocarcinoma MDR and be modified by Apatinib treatment." (PMID 31570733, 2019). "The alteration in the Bax/Bcl-2 ratio towards apoptosis as shown in this study suggests that AFAP1-AS1 can serve as a pro-survival factor by regulating pro-apoptotic signal transduction pathways, playing a role in the malignant phenotype of lung adenocarcinoma." (PMID 40650307, 2025). "In the TCGA dataset of lung adenocarcinoma, expression of MCL1, BCL2, BCL2L2, and BCL2A1 was significantly higher in non-tumor relative to tumor cells." (PMID 39122703, 2024). "Indomethacin, however, did not decrease expression of Bcl-2, Bcl-XS/L or Mcl-1 in GLC4 or GLC4-Adr which is in contrast to results described for lung adenocarcinoma cell lines." (PMID 15812552, 2005).
Stroke (82 papers, 2009 to 2025). Sudden impairment of blood flow to a part of the brain due to occlusion or rupture of an artery to the brain. "Another possible mechanism underlying the deleterious effects of stress on stroke outcome is through the protooncogene bcl-2." (PMID 32477259, 2020). "A SIRT1-dependent increase in Bcl2 has also been reported in a stroke context after curcumin pretreatment and has been linked to anti-inflammatory properties." (PMID 33519368, 2020). "Moreover, aging aggravates brain damage after stroke, because the reduction associated with aging in basal Bcl-2 expression in the brain exacerbates nerve damage by increasing cell apoptosis after stroke." (PMID 35387672, 2022). "Furthermore, the present study also found that the well-known anti-apoptotic protein Bcl-2 is implicated in the IP-induced improvement of neurological outcomes after stroke, as reported in previous studies." (PMID 26086415, 2015). "In addition, Apaf-1 (apoptotic associated factor 1), FADD (Fas (TNFRSF6)-associated via death domain) and Bcl-2, up regulated in female cardioembolic stroke, have all been associated with female cell death following stroke." (PMID 25036109, 2014). "In contrast, anti-apoptotic proteins, like Bcl2 and Bcl-XL, play a crucial role in enhancing neuronal survival and minimizing brain infarct volume in both reperfusion and permanent occlusion stroke models." (PMID 40076473, 2025). "Consistent with our findings, a previous study reported that OXT upregulated Bcl-2 expression in a mouse stroke model." (PMID 40143166, 2025). "The results showed that starting physical exercises within 6 hr after the stroke increased the apoptotic factors such as caspase 3 and Bax/BCL-2 ratio while 24 and 72-hour groups showed improvement in these apoptotic factors." (PMID 40896700, 2025). "A previous study in post-stroke mice demonstrated that Com-B exerts its anti-apoptotic effects on hippocampal neurons by regulating the expression of BAX/BCL-2 and caspase-3." (PMID 40649809, 2025). "Compared with the sham mice, the stroke mice showed an increase in the levels of Bax and cleaved caspase-3 and a significant decrease in the levels of Bcl-2, suggesting that apoptosis had occurred." (PMID 38786094, 2024). "Western blotting showed that stroke + MT mice exhibited lower Bax and cleaved caspase 3 levels and higher Bcl-2 levels than the stroke group, suggesting that MT inhibited apoptosis in mice." (PMID 38786094, 2024). "The increased amount of Bcl-2 in HBOC is beneficial in this respect to further defend the brain tissue against stroke." (PMID 36936654, 2023). "What’s more, the expression of the caspase-3 and Bax significantly increased, and the Bcl-2 in cerebral cortex of penumbra was decreased after stroke (p < 0.05, p < 0.01)." (PMID 37153779, 2023). "In short, circUSP36 inhibits astrocyte apoptosis and reduces neuronal damage after stroke through the miR-139–3p/SMAD3/Bcl-2 axis." (PMID 38203348, 2023). "Estrogen replacement stimulated early post-ischemic expression of bcl-2 and bfl-1 and reduced stroke-related damages." (PMID 37180115, 2023). "Similar findings were also present in stroke mice in vivo, where overexpression of serpinA3N reduced p‐p38, Bax/Bcl‐2, and cleaved Caspase‐3/Caspase‐3." (PMID 34897996, 2022). "Some studies have shown that MSCs transplantation would inhibit neuronal apoptosis by inducing the expression of Bcl-2, a proto-oncogene in a stroke model, which has been proved to regulate the expression of apoptosis." (PMID 35625017, 2022). "In another study, AT showed its protective effects by reducing the Bax/Bcl2 ratio in a stroke model induced by middle cerebral artery occlusion." (PMID 35096297, 2021). "The protein expression levels of prosurvival/antiapoptotic molecules, p-AKT and Bcl-2, in the core region of the post-stroke brain were then seen to be higher in the PCE-treated group than in the vehicle-treated group after tMCAO." (PMID 35052603, 2021).
Stroke (continued). "The expressions of antiapoptotic protein Bcl-2 and proapoptotic protein Bax were tested in the peri-infarct cortex on day 14 after stroke to further research how LV-APN-EPCs treatment suppressed cellular apoptosis." (PMID 33746885, 2021). "Although the specific mechanism has yet to be established, miR-124 also upregulated the antiapoptosis proteins Bcl-2 and Bcl-xl after stroke and exerted antiapoptotic effects." (PMID 34868302, 2021). "Elevated bcl-2 expression in various neurodegenerative disorders is known to be protective against apoptosis and necrosis, and up-regulation of bcl-2 in the ischemic penumbra occurs during stroke." (PMID 32477259, 2020). "NSTC also shows anti-apoptotic activity against stroke by down regulating the apoptosis signaling pathway and Bax levels, up-regulating Bcl-2 expressions." (PMID 33292339, 2020). "Upregulation of Bcl-2 in brain tissue with ischemic injury is thought to play an important role in post-stroke neuroprotection." (PMID 31167655, 2019). "Our data showed that CaMKK regulates apoptosis in the neonatal stroke brain, as pharmacological inhibition of CaMKK β after HI downregulated the level of Bcl-2 and upregulated the pro-apoptotic protein, Bax." (PMID 31027360, 2019). "Histone deacetylase (HDAC) inhibitors are well known to be neuroprotective in stroke models because they enhance the expression of anti-apoptotic proteins such as B-cell lymphoma 2 (Bcl2)." (PMID 31027360, 2019). "Previous study showed that resveratrol significantly downregulates cleaved caspase-3 and bax expressions, upregulates bcl-2 expression in stroke condition." (PMID 32257906, 2019). "This is consistent with our previous work showing that CaMKK β KO brains display lower Bcl-2 compared with WT controls in adult mice after stroke, further supporting the role of CaMKK in cell survival post-stroke." (PMID 31027360, 2019). "When compared with sham-operated group (reference as 1), protein expression of Bcl-2 and Bcl-xL was markedly reduced by stroke at both 6 (F =47.5, p<0.001; F =16.2, p<0.05) and 24 h (F =60.0, p<0.001; F =8.3, p<0.05)." (PMID 30090648, 2018). "It is established that increasing the expression level of Bcl-2 can obviously reduce the impact of stroke in neuroprotective treatments." (PMID 26771636, 2016). "Intranasal administration of apelin-13 significantly suppressed the caspase-3 activation and increased the survival gene Bcl-2 after stroke, providing an antiapoptotic mechanism of apelin-13 in the ischemic brain." (PMID 26391329, 2015). "Over-expression of anti-apoptotic proteins such as Bcl-2 and Bcl-xL have been shown to promote cell survival after focal cerebral ischemia, whereas Bcl-2 knockout exacerbated brain damage in stroke." (PMID 24671253, 2014). "Knocking-down other stroke-induced miRNAs miR-497 and miR-15a was also reported to be beneficial by increasing the expression of their common target Bcl2 which is an important anti-apoptotic protein." (PMID 23516428, 2013). "Finally, overexpression of Tmem30a also reduced apoptosis marker cleaved caspase‐3 (CC3) and necroptosis marker (p‐MLKL) and increased anti‐apoptosis marker Bcl‐xL and BCL‐2 in the penumbra regions 24 h after stroke." (PMID 40104262, 2025). "Recent study elucidated its anti-angina mechanism to ameliorate atherosclerosis and stroke via exerting antioxidant and anti-inflammatory effects by counteracting the inflammation pathway and necrosis via increasing B cell/lymphoma 2 (BCL-2), lowered caspase-3 and IL-6." (PMID 41184328, 2025). "However, the dCas9-VP64 system prevented Bcl2 downregulation when the stroke induced mice were treated with dCas9/CaP/PEI-PEG-bHb." (PMID 39239521, 2024). "Imbalances between Bcl-2 and caspase-3 are significant evidence of apoptosis, which is considered an influential factor in rapidly occurring neuronal cell death and the decline of neurological function after stroke." (PMID 38500994, 2024).
Stroke (continued). "CircUSP36 attenuates stroke-induced brain injury through the miR-139-3p/SMAD3/Bcl2 signaling axis and circUSP36 could be a potential therapeutic target for IS." (PMID 38682035, 2024). "In addition, circ_Dlgap3_1, circ_Tasp1_7, circ_Herc3_2, and circ_Chd2_24 targeted the antiapoptotic protein, Bcl-2, as well as apoptotic protease activating factor 1, supporting their participation in the apoptotic process after stroke." (PMID 34868302, 2021). "Moreover, the Bcl-2/BAX ratio in the stroke groups was 0.4 at both 1 and 3 days but significantly increased in both IPostE (***p < 0.001, 1.8 at 1 day and 0.9 at 3 days) and MPostE groups (***p < 0.001, 2.2 at 1 day and 1.9 at 3 days)." (PMID 33664650, 2021). "Furthermore, our data demonstrated that TGR5 knockdown significantly reverses the neuro-protection of TUDCA on stroke outcomes, as well as increasing BCL-2 and decreasing BAX and cleaved caspase-3 expression." (PMID 33261652, 2020). "Previous studies have demonstrated that various neuroprotective treatments may have the capacity to reduce the impact of stroke via increased expression levels of either Bcl-2 or Bcl-xL50,51." (PMID 31320660, 2019). "The Bcl-2 protein family is composed of pro-apoptotic (Bax, Bad) and anti-apoptotic (Bcl-2, Bcl-xl) members, which are major regulators of the mitochondrial apoptotic pathway, and are involved in the occurrence and development of stroke." (PMID 30618576, 2018). "Furthermore, compared with combination group treated at 5 and 6 h after ischemia, the Bcl-2 signals were strengthened in combination group treated at 4.5 h after stroke." (PMID 29681849, 2018). "The expressions of Nestin and Bcl-2 proteins were remarkably up-regulated by PE after stroke." (PMID 29167635, 2017). "In addition, several studies have shown that exercise or MSCs transplantation inhibits the apoptosis of neurons through inducing the expression of survivin or bcl-2 or both in a model of stroke." (PMID 26342636, 2015). "Indeed, corticosterone is known downregulate the expression of the cell survival gene Bcl-2 that is important for stroke outcome." (PMID 26338025, 2015). "Additionally, a DHA-enriched diet was shown to prevent microglial activation in a mouse stroke model, reduce ischemic lesion size, and increase levels of the anti-apoptotic molecules Bcl-2 in the CNS." (PMID 26685193, 2015). "In addition, Bax and Bcl-2 are suggested to be distinct regulators of apoptosis in the early stages of stroke." (PMID 24348730, 2013). "Importantly, the decreased Bcl-2/Bax ratio is described in animal stroke models." (PMID 39062133, 2024). "For example the blockage by PACAP of stroke induced c-Jun mRNA expression, supports the idea that it blocks apoptosis through an inhibition of the expression of proteins such as bax and a concomitant stimulation of BCL2 or BCL-XL as already shown in other experimental models." (PMID 33551991, 2020). "Western blot and immunofluorescence assay indicated that HSHS10.5 decreased Bax/Bcl-2 ratio and suppressed caspase-3 activation, while the phosphorylation of ERK1/2 and CREB was upregulated in a stroke rat model after HSHS treatment." (PMID 36793760, 2023). "The increased survival rate of genetically modified MSCs, generated via the co-overexpression of BCL2 + BDNF and BCLXL + BDNF, increases the likelihood of transplant survival after a stroke procedure, such as transplantation." (PMID 37371846, 2023). "We found a striking decline of Bcl-2 and apparent activation of Bax and caspase-3, accompanied by more TUNEL/CD31 double-positive cells in the peri-ischemic cortex after stroke." (PMID 35308117, 2022). "And the level changes of Bax, Bcl-2, MMP, and Caspase 3 were all detected in stroke cell or animal models after polyphenols administration." (PMID 34257802, 2021).